GPX4 (glutathione peroxidase 4)
Diseases named in the same sentence as GPX4 in open-access papers (continued):
Sharing a sentence is not in itself a finding about the gene and the disease.
cervical cancer (continued). "Our finding provides new insights into the mechanism by which circACAP2 regulates cervical cancer by miR-193a-5p/GPX4." (PMID 35847361, 2022). "The inhibition of miR-193a-5p or GPX4 overexpression repressed the circACAP2 depletion-induced levels of lipid ROS, iron, and Fe2+ in cervical cancer cells." (PMID 35847361, 2022). "constructed a new prognosis predication model based on 8 risk-related PRGs (GPX4, GSDME, GZMA, GZMB, IL1B, NOD1, PRKACA, and TNF) in cervical cancer, which had good predictive ability (AUC = 0.794)." (PMID 35912258, 2022). "We concluded that circular RNA circACAP2 repressed ferroptosis of cervical cancer during malignant progression by miR-193a-5p/GPX4." (PMID 35847361, 2022). "Downregulation of circACAP2 inhibited the viability of cervical cancer cells; however, a miR-193a-5p inhibitor or GPX4 overexpression could reverse these effects." (PMID 40161373, 2025). "In addition, Gboxin reduced the levels of GPX4 and Nrf2 in cervical cancer cells under low-glucose conditions, and these two proteins not only regulated ferroptosis but also played key roles in inhibiting cell apoptosis." (PMID 39859216, 2025). "After knockdown of ACSL4 expression in cervical cancer cells, the anticancer effect of oleanolic acid was counteracted, resulting in a decrease in reactive oxygen species and GPX4 levels, suggesting that OA activates ferroptosis in cervical cancer cells by promoting ACSL4 expression." (PMID 38292937, 2024). "And the cell death of cervical cancer cells caused by DHA, accompanied with depletion of GPX4 and GSH, could be attenuated by ferroptosis inhibitors." (PMID 37065442, 2023). "Indeed, limited studies have been conducted to identify the role of GPX4 in inducing ferroptosis in cervical cancer cells." (PMID 37025659, 2023). "MiR-193a-5p targets GPX4 mRNA and reduces GPX4 expression in cervical cancer cells." (PMID 37025659, 2023). "Therefore, we concluded that circular RNA circACAP2 repressed ferroptosis of cervical cancer during malignant progression by miR-193a-5p/GPX4." (PMID 35847361, 2022). "The knockdown of circACAP2 inhibited the cervical cancer cell viability, but the miR-193a-5p inhibitor or GPX4 overexpression could reverse the effect in the cells." (PMID 35847361, 2022). "The results demonstrate that Gboxin significantly decreased the mRNA levels of GPX4, FSP1, and SLC7A11 in cervical cancer cells cultured under low-glucose conditions." (PMID 39859216, 2025). "Triptolide induces ferroptosis in cervical cancer cells by downregulating NRF2, which leads to decreased GPX4 and xCT expression, resulting in increased lipid peroxidation and tumor growth inhibition." (PMID 40895556, 2025). "It has also been reported that triptolide can significantly reduce the expression of NRF2, leading to corresponding inhibition of NRF2 downstream targets GPX4 and SLC7A11, and finally promoting ferroptosis in cervical cancer cells." (PMID 40821694, 2025). "On one hand, propofol and paclitaxel can activate the apoptosis pathway in cervical cancer cells; on the other hand, their combination can also induce ferroptosis by regulating the SLC7A11/GPX4 pathway." (PMID 37891669, 2023). "During the SCC stage, cervical cancer epithelial cells acquire pronounced anti-ferroptotic capabilities SCC cells exhibit upregulated expression of anti-ferroptosis genes, including GCLM, GCLC, GSR and GPX4." (PMID 41479924, 2025). "Under hypoxia-like conditions, cervical cancer cells increase SLC7A11 expression through KDM4A SUMOylation at the K471 site, which reduces H3K9me3-mediated repression of SLC7A11, thereby enhancing GPX4 levels and promoting ferroptosis resistance." (PMID 40895556, 2025). "In addition, Cornichon family AMPA receptor auxiliary protein 4 (CNIH4) is upregulated in cervical cancer, CHIH4 promotes tumor progression by inhibiting ferroptosis by enhancing SLC7A11-mediated cystine import, boosting glutathione synthesis and GPX4 activity." (PMID 40895556, 2025).
cervical cancer (continued). "Similarly, our results showed that GPX4, an anti-lipid peroxidation gene, increased in SCC and erastin-induced cervical cancer cell lines suggesting that cervical cancer cells were able to clear excess lipid peroxide, and thereby to maintain cancer cell survival." (PMID 35422066, 2022).
Infertility (28 papers, 2015 to 2025). "Overall, these novel findings suggest that aberrant endometrial GPX4 expression with elevated levels of lipid peroxidation is one of the causes of recurrent implantation failure and infertility in women." (PMID 38044324, 2024). "Especially, it has been found that proteins LMNA and GPX4 are associated with diseases such as genetic disorder, embryo death, and infertility (p < 0.05)." (PMID 38561386, 2024). "GPX4-null mice undergo embryonic lethality, whereas conditional GPX4-mutant mice result in ferroptosis, neurodegeneration, loss of antiviral immunity, infertility, and ischemia-reperfusion injury in the kidney and liver." (PMID 35453641, 2022). "In S8/Gss−/− mice, decreased Gpx4 and increased Alox15 levels caused testicular ferroptosis, abnormal spermatogenesis, reduced sperm concentration, and morphological defects, ultimately leading to infertility." (PMID 40331931, 2025). "Additionally, the association of genetic polymorphisms of the gpx4 gene with infertility was shown in some exceptional cases." (PMID 41586246, 2025). "Because of the prominent expression of ACSL4 in uterine epithelium, we speculated that inactivation of Acsl4 may rescue infertility caused by Gpx4 depletion in the uterine epithelium." (PMID 38044324, 2024). "GPX4 knockout mice experience stillbirth during embryonic development, and sperm lacking GPX4 are highly susceptible to oxidative damage, resulting in infertility." (PMID 38493165, 2024). "Notably, spermatocyte-specific Gpx4 deletion in mice causes severe testicular atrophy, reduced spermatogenesis, germ cell death, and infertility, highlighting its importance in male reproductive biology." (PMID 37505079, 2023). "Thus, the molecular reasons for the infertility of Gpx4-deficient individuals may not only be related to motility problems of the sperm but also to their inability to induce proper acrosome reaction for fertilization." (PMID 36077303, 2022). "Our study was able to provide a reason as to why there were different levels of concentrations of GPX4 enzyme between healthy and infertile women with endometriosis, as the genotype polymorphism rs713041 may have led to altered structure or function of GPX4 protein." (PMID 32679649, 2020). "For example, the spermatocyte-specific GPX4 knockout male mice presented a decrease in the number of spermatozoa and infertility." (PMID 40454210, 2025). "Comparing the variables in the three examined groups, elevated levels of ACSL4 were observed in infertile patients with urogenital infections and varicocele; GPX4 levels were similar in the three groups." (PMID 39273059, 2024). "Mice with uterine deletion of Gpx4 by a progesterone receptor (Pgr)‐Cre driver (Gpx4f/fPgrCre) show embryo implantation failure resulting in complete infertility, despite normal uterine morphology and structure." (PMID 38044324, 2024). "Some researchers found that the expression level of GPX4 significantly declined in infertile men diagnosed with azoospermia." (PMID 37801247, 2023). "Reduced GPX4 activity is also observed in the sperm of infertile patients, emphasizing its role in human spermatogenesis." (PMID 37505079, 2023). "A different study showed significantly lower GPx4 levels in sperm samples from 75 infertile men with respect to the controls." (PMID 35204134, 2022). "A genetic study on 73 men demonstrated that GPx4 expression is decreased in about 10% of infertile men and about 35% of men with oligoasthenozoospermia, with significantly decreased sperm motility and spermatozoa concentration." (PMID 35204134, 2022). "GPX4 appears to play a role in human spermatogenesis as well: a significant reduction in GPX4 expression is found in a number of infertile oligospermic men." (PMID 33665191, 2021). "Diaconu and coauthors reported a substantial decrease in expressing GPX4 in spermatozoa of the human infertile males who have been diagnosed with oligoasthenozoospermia." (PMID 34401649, 2021).
Infertility (continued). "With the same token, residual GPX4 activity was significantly reduced in infertile men compared to the controls, and particularly reduced in oligoasthenozoospermic men." (PMID 31382427, 2019). "These authors also report that, among examined subjects, all but 10% of the infertile men demonstrated a striking decline in GPX4 levels in sperm." (PMID 31382427, 2019). "In another study on murine model in 2009, it was further demonstrated that reduced Gpx4 levels lead towards infertility in males." (PMID 31382427, 2019). "The team established a correlation between excessive generation of glutathione peroxidase (GPx4) and infertility due to inhibition of ROS production." (PMID 28933362, 2017). "These facts suggest that the excessive generation of GPx4 protein of spermatozoa leads to infertility through enhanced suppression of ROS production." (PMID 26348888, 2015). "Enhancing Gpx4 expression alleviates ferroptosis-related infertility." (PMID 40331931, 2025). "In men, genetic polymorphisms of gpx4 were weakly associated with seminal plasma GPX activity (possibly because GPX4 is not a major GPX in seminal plasma, see later), but may account for infertility in exceptional cases." (PMID 41586246, 2025). "Furthermore, uterine epithelial‐specific Gpx4 deletion in adult mice by Ltf‐Cre (Gpx4f/fLtfCre) recapitulated the infertility phenotype." (PMID 38044324, 2024). "The comparisons of investigated variables in the groups of fertile men and infertile patients with varicocele or urogenital infections confirmed the hypothesis of a pathway of GPX4-independent ferroptosis in these altered conditions." (PMID 39273059, 2024). "It is found that uterine deletion of Glutathione peroxidase 4 (GPX4), a key factor in repairing oxidative damage to lipids, confers defective implantation, leading to infertility." (PMID 38044324, 2024). "This study was designed for investigating the mRNA expression levels of the antioxidant genes NRF2, GPX4, SOD2, and CAT in infertile males before and after treatment with DPP and healthy controls." (PMID 34401649, 2021). "According to the findings, mRNA expression levels of antioxidant genes SOD2, GPX4, CAT and NRF2 are significantly lower in infertile case in comparison with the healthy control." (PMID 34401649, 2021). "We also conclude that administering DPP in infertile males enhances the levels of expression of NRF2, GPX4, SOD2, and CAT genes and improves the semen quality including sperm count, semen volume, and morphology and motility of sperm." (PMID 34401649, 2021). "In accordance, the infertile men were shown to have low levels of GPX4 expression and activity in their semen, and the lack of GPX4 activity (measured by phosphatidylcholine hydroperoxide consumption) is particularly pronounced in oligoasthenozoospermic men." (PMID 41586246, 2025). "We could present further documents for supporting this hypothesis: altered expression of antioxidant genes NRF2, GPX4, SOD2, and CAT at mRNA levels are correlated to the greater risks of males' infertility." (PMID 34401649, 2021). "Therefore, this research aimed at the determination of the impact(s) of DPP on the levels of mRNA expression of antioxidant genes (NRF2, GPX4, SOD2, and CAT) in infertile male." (PMID 34401649, 2021).
Cerebral ischemia (27 papers, 2020 to 2026). Restriction of arterial blood supply to the brain associated with insufficient oxygenation to support the metabolic requirements of the tissue. "Reportedly, rhein is able to inhibit ferroptosis through the NRF2/SLC7A11/GPX4 signaling pathway, attenuate the damage caused by cerebral ischemia/reperfusion, and induce dose-dependent neuroprotective effects." (PMID 40070574, 2025). "We also discovered that GSH depletion and GPX4 inactivation cause lipoxygenase activation and calcium influx following cerebral ischemia injury, resulting in MPTP opening and mitochondrial dysfunction." (PMID 37891735, 2023). "In the peri‐infarct cortex, GPX4 significantly declined during the acute phase post‐cerebral ischemia (comparing with D0, p < 0.01 at D7, n = 4)." (PMID 40376919, 2025). "There is evidence of positive effects on Cu/ZnSOD, GPX1, and GPX4 activity in the cytosol of rat myocardium and brains during cardiac or cerebral ischemia." (PMID 39861168, 2025). "Contrastingly, within the hippocampal region, GPX4 expression followed a “decrease‐then‐increase” trend post‐cerebral ischemia, being lower at D7 (p < 0.05, n = 4), but surpassing baseline level by D28 (p < 0.01, n = 4)." (PMID 40376919, 2025). "Piceatannol protects against cerebral ischemia or reperfusion injury by inhibiting neuronal ferroptosis through the USP14/GPX4 axis, and ACSL4 in microglia fuels neuroinflammation." (PMID 41306421, 2025). "In the peri‐infarct cortex, the GPX4‐mediated antioxidant defense mechanism experienced impairment during the acute phase of cerebral ischemia, persisting into the chronic phase." (PMID 40376919, 2025). "Phellandrene is a drug used to treat cerebral ischemia, and it can inhibit ferroptosis by enhancing GPX4 expression and reducing hippocampal neuron damage in the process of cerebral ischemia-reperfusion injury." (PMID 38650626, 2024). "Increasing GPX4 activation using Ferrostatin‐1 decreased neuronal cell death after cerebral ischemia/reperfusion." (PMID 35698913, 2022). "In the present experiment, the application of rosiglitazone significantly inhibited changes in GPX4, the signature protein of ferroptosis following cerebral ischemia." (PMID 33889074, 2021). "Carvacrol, a drug indicated for the treatment of cerebral ischemia, is beneficial in inhibiting ferroptosis in gerbils by potentiating the expression of GPX4 and attenuating hippocampal neuronal damage during cerebral ischemia–reperfusion injury." (PMID 32848555, 2020). "In conclusion, the mechanism of ferroptosis during cerebral ischemia is related to the accumulation of intracellular Fe2+, lipid peroxides, and oxidative damage induced by the downregulation of GPX4." (PMID 32848555, 2020). "In this review, we have summarized the mechanistic relationship between ferroptosis and cerebral ischemia, including through iron overload, downregulation of glutathione peroxidase 4, and upregulation of lipid peroxidation." (PMID 32848555, 2020). "Taken together, these findings demonstrated that the Arip1 deficiency attenuated neuronal ferroptosis after cerebral ischemia by increasing endogenous Act A levels, thereby modulating the Act A/SMAD3 and p38 MAPK signaling pathways, ultimately influencing the SLC7A11/GPX4 pathway." (PMID 40965963, 2025). "Together, our findings indicate that heat shock protein beta-1 exerts neuroprotective effects against cerebral ischemia/ reperfusion injury by suppressing microglial ferroptosis and pro-inflammatory activation via modulation of the nuclear factor-κB/glutathione peroxidase 4 signaling axis." (PMID 40817730, 2025). "NRF2 activation orchestrates a coordinated defense against cerebral ischemia by transcriptionally repressing ferroptosis through the GPX4/SLC7A11 axis and iron metabolism regulation, while concurrently mitigating oxidative stress, neuroinflammation, and apoptosis." (PMID 41306421, 2025). "Se alleviates cerebral ischemia-induced neurological damage by activating GPX4 in IS." (PMID 38846099, 2024).
Cerebral ischemia (continued). "Deletion or inactivation of GPX4 can lead to lethal ferroptosis and neurological dysfunction, often manifesting as progressive cognitive impairment and impaired behavior in the context of cerebral ischemia." (PMID 37891735, 2023). "In this study, we built a model of brain ischemia–reperfusion to observe whether the SLC7A11/GSH/GPX4 and PDGFRβ/PIK/Akt signal pathways were involved in the process; most importantly, we evaluated whether these two pathways could be potential valid targets of DL-NBP treatment." (PMID 36909944, 2023). "Interestingly, compared to GPX4 expression during perinatal brain development, it decreased in glial cells in the adult human brain; however, GPX4 expression in astrocytes was found to be significantly upregulated in a cerebral ischemia model." (PMID 33762907, 2021). "Western blot analysis revealed that cerebral ischemia marginally induced the expression of NRF2 and significantly decreased the expression of SLC7A11, GPX4, and FTL (P < 0.05 vs. sham)." (PMID 40474971, 2025). "Our study has reported that the activity of glutathione peroxidase 4 (GPX4), a key regulator of ferroptosis, was significantly reduced after cerebral ischemia." (PMID 40965963, 2025). "Subsequently, we employed Western blot analysis and discerned remarkable shifts in GPX4, ACSL4, and TfR expressions within peri‐infarct cortical and hippocampal areas post‐cerebral ischemia." (PMID 40376919, 2025). "EA can inhibit neuronal ferroptosis after cerebral ischemia/reperfusion and attenuate cerebral ischemia/reperfusion injury by decreasing the content of GSH and ROS and downregulating the expression of GPX4." (PMID 40353059, 2025). "After cerebral ischemia, ferroptosis was significantly upregulated in rats in the MCAO/R group, as evidenced by decreased GPX4 levels and increased COX2 levels." (PMID 38427114, 2024). "Kaempferol has been shown to protect cerebral ischemia-reperfusion injured cells by inhibiting apoptosis and inhibit iron death by activating the Nrf2/SLC7A11/GPX4 signaling pathway." (PMID 38257230, 2024). "Cerebral ischemia triggers oxidative stress and ROS production, depleting GSH and inactivating GPX4." (PMID 37891735, 2023). "Treating MCAO rats with Naotaifang (a traditional Chinese herbal medicine compound) extract involves inhibition of acute cerebral ischemia-induced neuronal ferroptosis and neurobehavioral disorder through TFR1/DMT1 and SCL7A11/GPX4 pathways." (PMID 35264947, 2021). "GPX4 and GSH are endogenous inhibitors of ferroptosis, and their content is closely related to cerebral ischemia." (PMID 32848555, 2020). "GPX4 and GSH are endogenous ferroptosis inhibitors that are closely related to cerebral ischemia." (PMID 38650626, 2024). "Additionally, studies have indicated that Met upregulates GPX4, reduces MDA levels, and provides protection against neurological impairments following cerebral ischemia." (PMID 38846099, 2024). "We speculate that Dl-3-n-butylphthalide has a neuroprotective effect on focal cerebral ischemia/reperfusion, which may be mediated through ferroptosis-dependent SLC7A11/GSH/GPX4 signal pathway and PDGFRβ/PI3/Akt signal pathway." (PMID 36909944, 2023). "Administration of drug therapy can alleviate cerebral ischemia injury, and its mechanism includes inhibition of ferroptosis through the transferrin receptor 1/divalent metal transporter 1(TFR1/DMT1) and solute carrier family 7 member 11/glutathione peroxidase 4(SCL7A11/GPX4) pathways." (PMID 36552584, 2022). "However, currently, researchers are focusing on the effect of GPX4 and GSH rather than on the upstream mechanism of cerebral ischemia." (PMID 32848555, 2020).